SCN1A (sodium voltage-gated channel alpha subunit 1)
Diseases named in the same sentence as SCN1A in open-access papers (continued):
Sharing a sentence is not in itself a finding about the gene and the disease.
Encephalopathy (25 papers, 2012 to 2025). Encephalopathy is a term that means brain disease, damage, or malfunction. "Together, our study reveals a pathophysiological phenotype of SCN1A-deficient encephalopathy and suggests SD as a potential and targetable contributor to comorbidity mechanisms in this disorder." (PMID 37551713, 2023). "Here, however, we have identified a severe-striking SCN1A phenotype, early infantile SCN1A encephalopathy, that has a recurrent mutation at c.677 in almost all cases." (PMID 28794249, 2017). "We describe that the Thr226Met mutation is associated with a distinctive profound SCN1A encephalopathy." (PMID 28794249, 2017). "In other words, the evolution of Scn1a-deficient encephalopathy may reflect sustained proexcitatory plasticity mechanisms rather than being solely determined by a static developmental defect." (PMID 37551713, 2023). "In practice, a SCN1A GOF variant has been acknowledged to lead to early infantile encephalopathy based on whole‐cell patch clamp findings, and in such cases, SCBs could show unexpected efficacy." (PMID 32400968, 2020). "Here, we review SCN1A-related encephalopathies, as well as the stem cell models used to explore their molecular basis." (PMID 36231081, 2022). "This review will focus on the latest research modeling the pathology of SCN1A-related encephalopathies with the iPSC technology." (PMID 36231081, 2022). "Many model systems for SCN1A-related encephalopathies approaches, both in vitro and in vivo, have been successfully used over the years to study genetic epilepsies." (PMID 36231081, 2022). "Encephalopathy caused by genetic abnormalities such as CPT2 and SCN1A is also being studied." (PMID 36233788, 2022). "Since most research on modeling pathology behind the SCN1A-related encephalopathy focused on identifying the neuronal deficits, it is of particular interest to see to what extent other systems might be involved." (PMID 36231081, 2022). "In a Japanese cohort of 87 patients with severe encephalopathy including ANE and AESD, but without underlying neurological disorders, three reportedly had SCN1A missense mutations." (PMID 36761411, 2023).
hemiplegic migraine (24 papers, 2011 to 2025). "Familial hemiplegic migraine 3 (FHM3) is caused by mutations in the voltage-gated sodium channel gene SCN1A coding for Nav1.1." (PMID 35655042, 2022). "Familial hemiplegic migraine mutations in SCN1A are commonly missense and cause gain-of-function effects such as a retarded inactivation, increased threshold-near persistent current, faster recovery and higher availability during repetitive stimulation." (PMID 32899972, 2020). "Mutations in CACNA1A, ATP1A2 and SCN1A genes are responsible for Familial hemiplegic migraine type 1 (FHM1), type 2 (FHM2), and type 3 (FHM3), respectively." (PMID 21731499, 2011). "Sporadic hemiplegic migraine caused by de novo SCN1A mutations have also been observed." (PMID 37139072, 2023). "Therefore, it is confirmed that SCN1A is one of the pathogenic genes for hemiplegic migraine." (PMID 35002916, 2021). "Familial hemiplegic migraine also may be caused by abnormalities within SCN1A gene." (PMID 33924914, 2021). "There is a genetic basis for certain migraines, including hemiplegic migraine, which include mutations in genes like CACNA1A (calcium channel), ATP1A2 (Na/K-ATPase), and SCN1A (sodium channel)." (PMID 40149800, 2025). "Another study focused on hemiplegic migraine and found that patients with mutations in CACNA1A, ATP1A2, or SCN1A tended to have a lower age at disease onset." (PMID 37305749, 2023). "Hemiplegic migraine is a rare monogenic MA subtype caused by mutations in three main genes - CACNA1A, ATP1A2 and SCN1A - which encode ion channel and transport proteins." (PMID 31226929, 2019). "Up to now, four causative genes have been described in hemiplegic migraine (HM): CACNA1A on chromosome 19p13 (FHM1, MIM #301011), ATP1A2 at 1q23 (FHM2, MIM #182340), SCN1A at 2q24 (FHM3, MIM #182389) and, recently, PRRT2 at 16p11.2 (MIM #614386)." (PMID 24498617, 2013).
myoclonic epilepsy (23 papers, 2009 to 2026). A group of epilepsy syndromes in which myoclonic seizures are a prominent feature. "A Japanese groups detected mutation in SCN1A in 77-82% of patients with severe myoclonic epilepsy of infancy (Dravet)." (PMID 24665294, 2013). "Thus, most cases of SCN1A-associated pediatric severe myoclonic epilepsy (SCN1A-SMEI) and ICE-GTC are the result of de novo pathogenic variants." (PMID 40003892, 2025). "In 2010, we conducted a study to identify pathogenic variants of the SCN1A gene using the Sanger sequencing method and successfully reported cases of novel SCN1A mutations in Indonesia in patients with severe myoclonic epilepsy in infancy (SMEI) and borderline SMEI (SMEB)." (PMID 38649973, 2024). "Additionally, a study showing the efficacy of PER in a newborn with early myoclonic epilepsy with SCN1A mutation suggests PER is SCN1A-mutation-specific." (PMID 39165469, 2024). "De novo null mutations in SCN1A result in severe myoclonic epilepsy of infancy." (PMID 24355397, 2013). "The individual carrying the benign T1250M variant had myoclonic epilepsy, attributed to a pathogenic TBCK variant identified after SCN1A testing." (PMID 39838578, 2025). "In two children with severe myoclonic epilepsy of infancy without SCN1A gene mutations, LHON onset included frequent myoclonic and tonic seizures, initially managed with valproate." (PMID 40718267, 2025).
developmental delay (22 papers, 2013 to 2026). "Three (7%; IDs 27–29) patients were found to have SCN1A variants; they experienced their first unprovoked seizures between the age of 24–28 months of life, and all had developmental delay." (PMID 34469436, 2021). "De novo variants in SCN1A are an increasingly recognized cause of an early-onset seizure and developmental delay." (PMID 28387369, 2017). "Here, we describe two additional siblings affected by mild familial myoclonic epilepsy, cognitive delay, slurred speech, abnormal gait and hypotonia, responsive to levetiracetam, both carrying two novel missense variants in SCN1A inherited from asymptomatic parents." (PMID 39200163, 2024). "We evaluated whether different seizure types, family history, abnormal brain MRI, or developmental delay were associated with specific SCN1A mutation types or locations within the gene." (PMID 30185235, 2018). "SCN1A:p.I1523L is also a novel variant however a different substitution affecting the same amino acid, p.(I523T), has been recorded in a female patient with FS onset at 6 years of age, inducing developmental delay, and evolving to tonic–clonic and SE in adulthood." (PMID 38891831, 2024). "In our cohort, several genes were frequently implicated in cases of genetic epilepsy and developmental delay, including PRRT2 (n:2), KCNQ2 (n:2), SCN1A (n:2), PLA2G6 (n:2), and KDM6A (n:2)." (PMID 40083435, 2025).
Intellectual disability (22 papers, 2011 to 2025). "If we were to subtract the cost of every single gene test from C1's cost analysis (cost for batten screen, CDKL5, SCN1A gene sequencing, Rett gene sequencing, ATP7A for Menkes disease, and X-linked mental retardation-sequencing of a panel of 7 genes), the excess cost would have still been $13,055." (PMID 27243033, 2016). "Of the genetic defects found outside the MD gene panel, seven genetic defects were found in genes present in the intellectual disability gene panel (ARID1B, SCN1A, ASPM, CTNNB, KDM6A, SMARCA4 and SETBP1)." (PMID 25735936, 2015).
autism spectrum disorder (17 papers, 2012 to 2025). A spectrum of developmental disorders that includes autism, and Asperger syndrome. "Previous studies report a potential susceptibility region at the chromosomal locus 2q including SCN1A, SCN2A and SCN3A genes for autism spectrum disorder (ASD)." (PMID 30071822, 2018). "Besides several epileptic and non-epileptic conditions, SCN1A gene mutations link with autism spectrum disorder, offering a genetic base for the spectral belonging of autism spectrum disorder to SeLFE." (PMID 37388546, 2023).
cardiac arrhythmia (16 papers, 2013 to 2025). Any disturbances of the normal rhythmic beating of the heart or MYOCARDIAL CONTRACTION. "This is probably due to SCN1A expression in the heart, not only in the brain, and the dysfunction of Nav1.1 causing cardiac arrhythmia, which contributes to SUDEP in DRVT." (PMID 36231081, 2022). "Our previous work using induced pluripotent stem cell cardiac myocytes derived from patients with DEE with variants in SCN1A predicted cardiac arrhythmia prior to clinical diagnosis in 1 of the patients." (PMID 35603785, 2022). "Late Na+ current blockers have been proposed as possible treatment options for cardiac arrhythmia causing mutations of SCN5A that led to similar gain of function effects as seen here for SCN1A." (PMID 31730442, 2019). "In this study, we sought to determine if alterations in mitochondrial bioenergetics and reactive oxygen species are present in a mouse model of Scn1a-linked DS, as these pathways may contribute to the development of arrhythmias and SUDEP." (PMID 39390983, 2024). "Importantly, we found that male Scn1a−/+ mice are more susceptible to cardiac arrhythmias than female Scn1a−/+ mice." (PMID 39390983, 2024). "Previously, mutations in Scn1a have been linked to arrhythmia." (PMID 39390983, 2024). "Specifically, we examined whether Scn1a+/− mice exhibit differences in mitochondrial respiratory pathways, imbalances in ROS production and scavenging, and overall are more susceptible to cardiac arrhythmia development." (PMID 39390983, 2024). "Male Scn1a−/+ mice were also more susceptible to cardiac arrhythmias under increased workload." (PMID 39390983, 2024). "However, our data suggest that male Scn1a−/+ mice may be more susceptible to cardiac arrhythmias following onset of seizures." (PMID 39390983, 2024). "We propose that, in addition to neuronal dysfunction, Scn1a haploinsufficiency produces altered cardiac electrical function and arrhythmias, providing a cardiac contribution to the mechanism of SUDEP." (PMID 24155976, 2013). "We propose that, in addition to neuronal hyperexcitability, SCN1A haploinsufficiency alters cardiac electrical function and produces arrhythmias, providing a potential mechanism for SUDEP." (PMID 24155976, 2013). "Therefore, we hypothesized that that under times of increased physiological stress or demand on the heart would reveal an underlying predisposition to cardiac arrhythmias in male but not female Scn1a−/+ mice." (PMID 39390983, 2024). "In systemically knockout heterozygous SCN1A+/- mice, severe arrhythmias were found to be characterized by prolonged PR interval, increased heart rate variability, and even atrioventricular block, suggesting that changes in the cardiac SCN1A may be related to SUDEP." (PMID 35002916, 2021). "Of hearts that did experience VT or VF, the time between diamide administration and the first incidence of arrhythmia was also not significantly shorter in Scn1a−/+ mice (15.53 ± 4.43 in Scn1a+/+ vs. 10.38 ± 2.78 in Scn1a−/+; p = 0.70)." (PMID 39390983, 2024). "We report that Scn1a-R1407X heterozygous mice have increased TTX-R, but not TTX-S, cardiac INa, as well as altered AP and ECG properties, EADs, and arrhythmias that produce SUDEP-like events." (PMID 24155976, 2013).
status epilepticus (16 papers, 2009 to 2026). Status epilepticus is defined as a continuous seizure lasting more than 30 min, or two or more seizures without full recovery of consciousness between any of them. "Patient 3: A 21-year-old male with a heterozygous SCN1A nonsense mutation (c.1141C>T; p.Gln381Ter) developed focal motor seizures with status epilepticus at 14 months of age." (PMID 41573391, 2025). "Patient 21, a 10-month old female with status epilepticus (25 min long) during COVID-19 infection shared the same SCN1A:c.474-1G>A variant with her father." (PMID 38891831, 2024). "We herein demonstrated that de novo splicing variants in the SCN1A were present in two patients and in the monozygotic younger sister of one patient, and that these patients died due to status epilepticus." (PMID 38174099, 2023). "Of the 20 patients, three had status epilepticus (SE); two harbored SCN1A variants and the other had a DNM1 variant." (PMID 36119689, 2022). "Nevertheless the Scn1a knockout rats certainly reflect the pathogenesis of NaV1.1 haploinsufficiency and are less affected by additional factors such as status epilepticus, frequent spontaneous seizures, malnutrition, and premature death." (PMID 36998780, 2023). "HE and Nissl staining revealed that Lira alleviated neuronal damage following Scn1a KO-induced status epilepticus." (PMID 32184723, 2020). "Less than half (6/13) of the PCDH19-DS patients had status epilepticus although this is a highly frequent feature in SCN1A-DS (93/113, p<0.007)." (PMID 19214208, 2009). "Thus, the MEMRI findings in Scn1a+/− rats purely reflect the Scn1a pathology with a minimal influence of spontaneous seizures, status epilepticus, and malnutrition." (PMID 36998780, 2023). "Contrastingly, Scn1a+/− mice show spontaneous seizures more frequently from the third postnatal week and showed premature death in about 35% of pups, mainly due to status epilepticus and/or malnutrition." (PMID 36998780, 2023).
focal epilepsies (14 papers, 2009 to 2025). "With the wide application of gene sequencing technology, some focal epilepsies have been found to be associated with SCN1A variants." (PMID 35571373, 2022). "However, a signal at 2q24.3 (containing SCN1A) in focal epilepsy approached but did not achieve significance." (PMID 25087078, 2014).
Rett syndrome (14 papers, 2016 to 2024). A severe neurodevelopmental disorder affecting the central nervous system.
Anxiety (13 papers, 2017 to 2025). Intense feelings of nervousness, tension, or panic often arise in response to interpersonal stresses. "Thus, our result indicates that dysregulation of inhibitory transmission via α2/3-GABAAR is involved in the mechanism underlying anxiety-like behavior in Scn1a deficit mice." (PMID 37849734, 2023). "Scn1a mutants, Gabrb3+/N328D knock-in mice, and young Scn2a mutant mice were also revealed to exhibit normal anxiety levels in several paradigms." (PMID 41585885, 2025). "Scn1a mutants displayed modest increase in anxiety, consistent with Nav1.1 haploinsufficiency models that increased thigmotaxis in the OF test." (PMID 41585885, 2025). "In this study, we investigated efficacy of KRM-II-81 on DS by using Scn1a deficit mice and illustrated that KRM-II-81 ameliorates hyperthermia-induced seizure susceptibility and anxiety-like behavior in these mice." (PMID 37849734, 2023). "Adult Scn1a+/- mice have been reported to display altered anxiety-related behaviors, impaired sociability and spatial memory." (PMID 31697745, 2019). "While Scn1a haploinsufficiency is known to cause sleep and circadian abnormalities, hyperactivity, autistic- and anxiety-like behavior in mouse models, these comorbidities have not been previously investigated in a systematic way in scn1lab mutant zebrafish." (PMID 28812061, 2017). "Finally, delayed Scn1a haploinsufficiency induction provoked hyperactivity, anxiety and social attitude impairment at levels comparable to age matched P2-induced mice, while it was associated with a better cognitive performance, with P60-induced mice behaving like the control group." (PMID 37812819, 2024). "In contrast, behavioral analysis revealed that male, but not female, Scn1a+/− mice displayed motor hyperactivity, and abnormal performance on tests of fear and anxiety and learning and memory." (PMID 31830809, 2020). "Notably, percent time in the center of the open field and stereotypic counts were similar in Scn1a +/KI mice compared to Scn1a +/+ mice, indicating no apparent evidence of increased anxiety." (PMID 33411788, 2021).
generalized tonic-clonic seizures (11 papers, 2013 to 2024). "The seizures of SCN1A variant patients were predominantly focal seizures, followed by generalized tonic-clonic seizure (GTCS), while several patients exhibited comorbid myoclonus, spasms, absence seizures, and atonic seizures." (PMID 38174099, 2023). "The first seizure type varied among the patients with an SCN1A mutation: febrile seizures in sixteen patients, myoclonic seizure in one patient, simple partial seizure in one patient and secondary generalized tonic-clonic seizure (GTCS) in one patient." (PMID 35663268, 2022). "The index patient with an SCN1A c.3969+2451G>C variant was an 11-year old male originally diagnosed with febrile seizures plus due to febrile generalized tonic clonic seizures at 23 months and afebrile GTCS at 26 months." (PMID 33411788, 2021).
West syndrome (11 papers, 2017 to 2025). "Variants in these patients and associated phenotypes are described as follow; two variants of SCN1A (c.1703G > A/p.R568Q, c.4176T > A/p.N1392K) were identified in two patients of unclassified EEES and one variant of ARX (c.1600G > C/p.A534P) in a West syndrome patient." (PMID 28387369, 2017). "SCN1A not only causes DS and GEFS+; other epileptic encephalopathies, such as Doose syndrome, EIMFS, West syndrome, LGS, RTT, and NEE, are also directly related to SCN1A." (PMID 35002916, 2021). "However, SCN1A was not reported in a recent review of West syndrome, indicating its rarity in this disease." (PMID 35002916, 2021).
Alzheimer disease (10 papers, 2016 to 2025). A progressive, neurodegenerative disease characterized by loss of function and death of nerve cells in several areas of the brain leading to loss of cognitive function such as memory and language. "However, SCN1A triplication was described in Alzheimer's disease, or 1q21.1 triplication was linked to facial dysmorphism, whereas a few aberrations in the form of partial chromosomal triplications were also described applying classical cytogenetic methods." (PMID 36028842, 2022). "SCN1A upregulation can be achieved by blocking the transcriptional inhibitory activity of a regulatory lncRNA from the SCN1A locus (SCN1ANAT) using 2OMe ASOs termed AntagoNATs (Alzheimer’s Disease)." (PMID 33996898, 2021).
familial hemiplegic migraine type 3 (10 papers, 2018 to 2024). "GoF SCN1A variants have been traditionally associated with familial hemiplegic migraine type 3 (FHM3)." (PMID 39200163, 2024). "Familial hemiplegic migraine type 3 (FHM3) was linked to a specific gene in 2005 after discovering a mutation in the SCN1A gene on chromosome 2q24 in three German families." (PMID 38731230, 2024). "Familial hemiplegic migraine type 3 (FHM3) is caused by gain-of-function mutations in the SCN1A gene that encodes the α1 subunit of voltage-gated NaV1.1 sodium channels." (PMID 34135733, 2021). "The familial hemiplegic migraine type 3 (FHM3) is seldom caused by mutations in SCN1A." (PMID 30498473, 2018).
myoclonic-atonic epilepsy (10 papers, 2016 to 2024). "Seldom, SCN1A variants are also associated with other forms of DEE, including myoclonic–astatic epilepsy (MAE, Doose syndrome), Infantile epilepsy with migratory focal seizures (EIMFS), West syndrome (WS) and Lennox–Gastaut syndrome (LGS)." (PMID 38785537, 2024).